MALAT1 (metastasis associated lung adenocarcinoma transcript 1)
Diseases named in the same sentence as MALAT1 in open-access papers (continued):
Sharing a sentence is not in itself a finding about the gene and the disease.
ischemic stroke (continued). "Collectively, these data demonstrate the mechanism underlying the invovlvement of MALAT1 in cerebral ischemia/reperfusion injury, thus providing translational evidence that MALAT1 may serve as a novel biomarker and therapeutic target for ischemic stroke." (PMID 33750458, 2021). "Furthermore, MALAT1 was one of the mostup-regulated oxygen deprivation-responsive endothelial lncRNAs in ischemic stroke,implying a critical role in protecting the cerebral microvasculature from cerebralischemic insults in mice (Zhang etal., 2016)." (PMID 31188931, 2019). "MALAT1 may exerts a protective effect after ischemic stroke via its anti-inflammatory roles in microvasculature." (PMID 29651234, 2018). "The functions of MALAT1 in ischemic stroke were identified recently." (PMID 29449542, 2018). "Endothelial-selective lncRNAs such as MALAT1 have been demonstrated to have a role in cerebral ischemia and may serve as promising regulators targeting cerebral endothelial dysfunction in ischemic stroke." (PMID 29651234, 2018). "Thus, increasing expression of MALAT1 in ischemic stroke affords protection." (PMID 34044272, 2021). "SNPs of MALAT1 may influence vulnerability to ischemic stroke." (PMID 33192490, 2020). "Therefore, up-regulation of MALAT1 could promote the development of ischemic stroke." (PMID 33613191, 2020). "Therefore, MALAT1 expression is augmented in brain endothelial cells under ischaemia, which may contribute to a potential therapeutic strategy for patients who have suffered ischaemic stroke." (PMID 30784209, 2019). "Silencing Malat1 severely aggravated the injury of primary BMEC cultures, and worsened neurological scores, sensorimotor functions, and brain infarct size in the mouse model of ischemic stroke." (PMID 35346266, 2022). "MALAT1 could bind to IL-6, E-selectin and MCP-1, which prevent OGD/R-induced inflammatory response in ischemic stroke by reducing the production of proinflammatory cytokines." (PMID 33613191, 2020). "Similarly, MALAT1 inhibits inflammation and oxidative stress in ICH, as in ischemic stroke." (PMID 37187956, 2023). "However, the function of MALAT1 has not yet been clearly characterized, and its neuroprotective effects in the pathological process of ischemic stroke are not totally understood." (PMID 35053294, 2022). "Also, silencing of lnc-MALAT1 raises the level of pro-apoptotic factor Bim and pro-inflammatory cytokines (including MCP-1 as well as E-selectin) in BMECs following oxygen-glucose deprivation (OGD), which is an in vitro mimic of ischemic stroke conditions." (PMID 33111743, 2020).
diabetic retinopathy (36 papers, 2014 to 2025). "Consistent with our findings, the MALAT1 rs3200401 (T/C) genotype was protective against diabetic retinopathy and associated with decreased disease susceptibility." (PMID 35053285, 2022). "Metastasis-associated lung adenocarcinoma transcript 1 (MALAT1) conserves LncRNAs that are involved in inflammation, cell death, and angiogenesis in diabetic retinopathy." (PMID 35010703, 2021). "In particular, in cases where VEGF treatment resistance exists (e.g., resistance due to VEGFR2 mutations in diabetic retinopathy), intervening in the circ-MALAT1/miR-96–5p/FOXK2 network may provide an alternative therapeutic strategy." (PMID 40997603, 2025). "MALAT-1 is equally linked to diabetic retinopathy and diabetic cataract." (PMID 37168992, 2023). "Numerous lncRNA have been linked to oxidative damage in diabetic retinopathy, including metastasis-associated lung adenocarcinoma transcript 1 (MALAT1), Hox antisense intergenic RNA (HOTAIR), nuclear paraspeckle assembly transcript 1 (NEAT1), Arid2-IR, OGRU, and HIF1 antisense RNA 2 (HIF1A-AS2)." (PMID 37627644, 2023). "The upregulation of MALAT1 in diabetic retinopathy decreased the transcription of antioxidant defense genes in retinal endothelial cells, and its knockdown protected the retina from oxidative stress in diabetic retinopathy." (PMID 36983051, 2023). "High levels of MALAT1 enhance retinal inflammation in diabetic retinopathy, suggesting that MALAT1 is likely also involved in regulating the inflammatory response of ocular diseases." (PMID 36700118, 2023). "Another molecule related to MALAT1 in diabetic retinopathy was glucose-regulated protein 78 (GRP78), in relation to endoplasmic reticulum stress (ERS)." (PMID 37762249, 2023). "High levels of Yap1 expressed in the retinas of mice with diabetic retinopathy upregulate MALAT1 and target VEGFA by regulating miR-200b-3p." (PMID 36035997, 2022). "MALAT1, as an epigenetic player, has been often described in connection with cancer progression or as an inflammatory regulator in diabetic retinopathy." (PMID 35887000, 2022). "In diabetic retinopathy, MALAT1 also plays an integral part in the regulation of the Keap1-Nrf2-antioxidant defense system." (PMID 35207562, 2022). "The epigenetic regulation of inflammation by lncRNA MALAT1 in diabetic retinopathy was studied using human retinal endothelial cells (HRECs) and vitreous humor from diabetic patients." (PMID 36297381, 2022). "lncRNA MALAT1 knockdown in retinas of db/db mice resulted in amelioration of diabetic retinopathy as manifested by reduced apoptosis of retinal cells and pericytes." (PMID 27881904, 2016). "One of these complications, diabetic retinopathy, was recently shown to be influenced by lncRNA MALAT1 (metastasis-associated lung adenocarcinoma transcript 1)." (PMID 27881904, 2016). "Our aim was to investigate MALAT1’s role in mitochondrial dynamics in diabetic retinopathy." (PMID 40650203, 2025). "However, Lnc-RNA MALAT1 is mainly involved in diabetic retinopathy by regulating angiogenic pathways." (PMID 37762249, 2023). "MALAT1 activates Keap1′s transcription, thus impeding Nrf2 nuclear movement and inhibiting the transcription of the antioxidant response enzymes in HRECs, in vivo and in retinal microvessels from human donors with diabetic retinopathy." (PMID 37762249, 2023). "Whether the interaction between MALAT1 and miR-125b contributes to the redox homeostasis in diabetic retinopathy is worthy of investigation." (PMID 35207562, 2022). "Another study showed that MALAT1 competitively binds to miR-125b against vascular endothelial-cadherin, which may promote neovascularization in diabetic retinopathy." (PMID 35207562, 2022). "Thus, lncRNA MALAT1 modulated antioxidant defense in diabetic retinopathy via its interaction with the Keap1/NRF2 pathway." (PMID 36297381, 2022).
diabetic retinopathy (continued). "According to Radhakrishnan R and Kowluru RA, the lncRNA MALAT1 can adjust the antioxidant defense in diabetic retinopathy through the Keap1/Nrf2 pathway, and inhibiting the lncRNA MALAT1 may help to protect the retina from oxidative damage and prevent or slow diabetic retinopathy." (PMID 38907191, 2024). "For instance, lncRNAs such as MALAT1 and MIAT have been extensively studied and demonstrated to be involved in the pathogenesis of diabetic retinopathy." (PMID 38907191, 2024). "Also, the role of MALAT1 in affecting mitochondrial DNA stability, leading to the development of diabetic retinopathy, cannot be ruled out." (PMID 40650203, 2025).
Insulin resistance (31 papers, 2016 to 2025). Increased resistance towards insulin, that is, diminished effectiveness of insulin in reducing blood glucose levels. "In line with our findings, a previous study also unveiled that decreased MALAT1 expression caused by exercise could suppress insulin resistance in T2DM via increasing miR-382-3p expression through synchronous inhibition of resistin." (PMID 37740187, 2023). "The MALAT1 rs3200401 SNP was identified as a risk factor for childhood obesity (p < 0.05) under the dominant and allelic models, and the CT heterozygous genotype was associated with the risk of increased BMI and with insulin resistance." (PMID 37104004, 2023). "Similarly, lncRNA metastasis-associated lung adenocarcinoma transcript 1 (MALAT1) was also increased in the obese mouse model’s liver and promoted insulin resistance." (PMID 33478141, 2021). "Contrary to this hypothesis, male and female Malat1-deficient mice gained as much weight, and developed insulin resistance to a similar extent as their Malat1+/+ littermates when studied up to eight months old on regular chow or a high-fat, high-sucrose diet." (PMID 29746487, 2018). "After studying the liver biopsies of NAFLD patients, it was stated that MALAT1 acts as a regulator of hepatic inflammation and fibrosis and of insulin resistance by targeting the C-X-C motif chemokine ligand 5 (CXCL5)." (PMID 41226441, 2025). "Conversely, the overexpression of MALAT1 led to lipid accumulation, thereby implicating MALAT1 in the development of hepatic steatosis and insulin resistance." (PMID 40002783, 2025). "So by increasing nuclear SREBP1c protein stability in the liver, MALAT1 can promote hepatic steatosis and insulin resistance." (PMID 41226441, 2025). "MALAT1 overexpression promotes lipid accumulation, hepatic steatosis, and insulin resistance by increasing the expression of SREBP-1c, a sterol regulatory binding protein that is activated mainly by insulin, and the target genes ACC1, ACLY, SCD1, and FAS." (PMID 38674413, 2024). "A positive correlation between MALAT1 gene expression and insulin resistance was observed in the subcutaneous adipose tissue (SAT) of patients, suggesting the involvement of lncRNAs in the pathogenesis of obesity." (PMID 38674413, 2024). "It was documented that MALAT1 interacted with SREBP1c mRNA to increase its stability, and in vivo MALAT1 siRNA injection prevented hepatic lipid accumulation and insulin resistance in ob/ob mice." (PMID 38203767, 2024). "The study found that Malat1-deficient males and females gained the same amount of weight and developed insulin resistance to a similar degree as MALAT1+/+ mice." (PMID 38674413, 2024). "In conclusion, MALAT1 induces hepatic lipid accumulation and insulin resistance by increasing the expression of SREBP-1c and target genes." (PMID 38674413, 2024). "High glucose levels can increase MALAT1 expression in endothelial cells and MALAT1 up-regulates resistin to reduce insulin resistance during exercise." (PMID 35163020, 2022). "A next-generation sequencing about T2DM discovers that the expression of MALAT1 and MIAT is raised and these abnormal levels have associations with insulin resistance." (PMID 34496971, 2021). "The deletion of MALAT1 impedes liver cells' development, indicating MALAT1 contributes to hepatic insulin resistance." (PMID 33622377, 2021). "As expected, aging induced robust glucose intolerance and insulin resistance in both male and female animals (compare Malat1+/+ mice between ages)." (PMID 29746487, 2018). "It has been reported that MALAT1 promotes hepatic steatosis and insulin resistance by increasing the stability of nuclear SREBP1-c, a key protein involved in fatty acid synthesis." (PMID 28933767, 2017). "In summary, MALAT1 induced hepatic lipid accumulation and insulin resistance by increasing SREBP-1c and target genes expression." (PMID 26935028, 2016).
Insulin resistance (continued). "The present study was designed to evaluate the role of MALAT1 in hepatic lipid metabolism and insulin resistance both in vitro and in vivo." (PMID 26935028, 2016). "In conclusion, our observations suggest that MALAT1 promotes hepatic steatosis and insulin resistance by increasing nuclear SREBP-1c protein stability." (PMID 26935028, 2016). "For instance, Malat1 was revealed to promote hepatic steatosis and insulin resistance by increasing nuclear SREBP-1c while Samd4 was associated with uncoupled mitochondrial respiration, where mitochondrial dysfunction was the key factor in NASH pathogenesis." (PMID 27677588, 2016). "This supports the thesis that MALAT1 plays a role in hepatic steatosis and insulin resistance." (PMID 38674413, 2024). "Thus, MALAT1 is suggested to promote hepatic steatosis and insulin resistance by enhancing triacylglycerol biosynthesis through the increase of nuclear SREBP-1c protein stability." (PMID 34078383, 2021). "In an experiment, lncRNA MALAT1 is at a raised level in mice with insulin resistance and may be a target of T2DM therapy." (PMID 34496971, 2021). "Similarly, previous work showed that the lncRNA, metastasis-associated lung adenocarcinoma transcript 1 (MALAT1), interacts with SREBP-1c to stabilize nuclear SREBP-1c protein and thereby promote hepatic steatosis and insulin resistance." (PMID 32295144, 2020). "Similarly, the lncRNA MALAT1 promoted hepatic steatosis and insulin resistance by increasing nuclear SREBP-1c stability." (PMID 32765426, 2020). "MALAT1 has been reported as an important agent in hepatic insulin resistance development." (PMID 32545342, 2020). "The role of MALAT1 in hepatic steatosis and insulin resistance has also been described." (PMID 30931332, 2019). "Moreover, MALAT1 can promote hepatic steatosis and insulin resistance via increasing nuclear SREBP-1c stability." (PMID 30931332, 2019). "Furthermore, it was shown that MALAT1 expression was increased in the liver of obese mice and promoted hepatic insulin resistance by activating the stability nuclear sterol regulatory element binding transcription factor 1c (SREBP-1C)." (PMID 30469430, 2018). "Importantly, MALAT1 was shown to be involved in the regulation of synaptic density, hepatic steatosis, and insulin resistance." (PMID 30469430, 2018). "Finally, injection of si-MALAT1 prevented hepatic lipid accumulation and insulin resistance in ob/ob mice." (PMID 26935028, 2016). "Additionally, MALAT1 could promote insulin resistance and hepatic steatosis through increasing the stability of nuclear SREBP-1c." (PMID 34828420, 2021). "Finally, MALAT1 may induce lipid accumulation and insulin resistance by increasing SREBP-1c and target gene expression." (PMID 32765426, 2020). "Based on these results, we examined whether absence of Malat1 would confer higher susceptibility to diet-induced fat accretion and insulin resistance." (PMID 29746487, 2018). "Interestingly, in addition to its roles in insulin resistance, the function and working mechanism of MALAT1 were also studied in neuronal process implying that this lncRNA might be an example of lncRNA linking both processes." (PMID 30469430, 2018). "ADMSCs attenuated insulin resistance through upregulation of IRS1 and downregulation of SREBP-1 and Malat1." (PMID 39500806, 2024). "Taken together, these findings demonstrate that absence of Malat1 does not attenuate nor accelerate diet-induced fat gain and insulin resistance." (PMID 29746487, 2018). "It is thus possible that besides a theoretically more insulin-sensitive WAT, other tissues have developed insulin resistance in the absence of Malat1, although this would require additional experimental characterization." (PMID 29746487, 2018). "The results showed MALAT1 expression was upregulated in PCOS cases, especially in insulin resistant (IR) PCOS subgroup, obese PCOS subgroup and non-hyperandrogenic (NHA) PCOS subgroup." (PMID 38424234, 2024).
nasopharyngeal carcinoma (31 papers, 2013 to 2025). A carcinoma arising from the nasopharyngeal epithelium. "MALAT1 (metastasis-associated lung adenocarcinoma transcript 1) was recently shown to be upregulated in nasopharyngeal carcinoma (NPC) cells and tissues." (PMID 33292252, 2020). "MALAT1 (Metastasis associated lung adenocarcinoma transcript 1) is a well-known oncogenic lncRNA that is upregulated in several types of tumors, including lung, breast, cervical, and nasopharyngeal cancers." (PMID 38835012, 2024). "Moreover, the diagnostic efficacy of MALAT-1 in other cancers, including digestive system tumor, gynecologic cancer and nasopharyngeal carcinoma also revealed robust results." (PMID 29254244, 2017). "MALAT1 has a role in cisplatin resistance in OSCCs and radioresistance in cervical and nasopharyngeal carcinomas." (PMID 40568293, 2025). "LncRNAs like MALAT1 and NEAT1 contribute to radioresistance, with MALAT1 modulating resistance in nasopharyngeal cancer via miR-1 inactivation and NEAT1 promoting resistance through the miR-204/ZEB1 axis." (PMID 40150019, 2025). "MALAT-1 is a promising diagnostic marker for detecting endometrial, breast, NSCLC, bladder, and nasopharyngeal carcinoma (NPC)." (PMID 38201661, 2024). "MALAT1 promotes EMT of nasopharyngeal carcinoma cells through de-repressing Capn4 by sponging miR-124 and mediates TGF-β1-induced EndMT by regulating TGFBR2 and SMAD3 through miR-145 in endothelial progenitor cells (EPCs)." (PMID 30871555, 2019). "For example, upregulation of APAF1-AS1, AL359062, and MALAT1 in nasopharyngeal carcinoma (NPC) and SNHG8, RP5-1039 K5.19, and TP73-AS1 in EBV associated-gastric cancer can be associated with cancer promotion." (PMID 39941858, 2025). "For instance, MALAT1 is significantly upregulated in nasopharyngeal carcinoma (NPC) specimens or cell lines." (PMID 28872613, 2017). "Analysis of the efficacy in other types manifested that MALAT-1 testing harvested an AUC of 0.84, specificity of 0.88 and DOR of 11.33 in identifying nasopharyngeal carcinoma, suggesting that MALAT-1 might be developed as a promising biomarker for nasopharyngeal carcinoma as well." (PMID 29254244, 2017).